IGF1R (insulin like growth factor 1 receptor)
Diseases named in the same sentence as IGF1R in open-access papers (continued):
Sharing a sentence is not in itself a finding about the gene and the disease.
seminoma (4 papers, 2018 to 2022). A radiosensitive malignant germ cell tumor found in the testis (especially undescended), and extragonadal sites (anterior mediastinum and pineal gland). "The upregulation of insulin growth factor receptor-1 (IGF1R) expression and signaling has also been found to contribute to acquired cisplatin resistance in an in vitro non-seminoma model." (PMID 35625709, 2022). "Our group has recently shown that IGF1R is expressed in approximately half of non‐seminomas and influences survival of non‐seminoma cells in vitro." (PMID 31179642, 2019). "The ELISA and immunoprecipitation assays indicated that unstimulated phospho‐IGF1R levels were generally low, with the only seminoma cell line, TCAM2, having detectable levels by IP." (PMID 29160922, 2018). "IGF1R was identified as highly expressed and activated in the GCT model cell lines of non-seminoma, with the highest expression in the acquired cisplatin-resistant cell line." (PMID 35625709, 2022). "The seminoma cell line TCAM2 was one of the most resistant lines to NVP‐AEW541 inhibition, consistent with a mild phenotypic response to IGF1R silencing, and the 2102 cell line, which demonstrated the lowest phospho‐AKT levels, was the most resistant." (PMID 29160922, 2018). "This is seen in the case of the seminoma cell line, TCAM2, which despite comparatively high basal levels of activated IGF1R among TGCT cell lines was among the least responsive to an IGF1R TKI." (PMID 31179642, 2019). "Expression of IGF1R was significantly higher in both nonseminomas and seminomas than in normal tissues (p = 0.005 and p = 0.013, respectively; two‐tailed t‐test with Welch's correction)." (PMID 29160922, 2018). "Overall, 73/148 (49%) nonseminomas expressed IGF1R and the majority of seminomas and germ cell neoplasia in situ cases were positive." (PMID 29160922, 2018).
T-cell lymphoma (4 papers, 2015 to 2024). "Patients with T-cell lymphoma have much lower levels of Klotho in their lymph nodes than in normal lymph nodes; the overexpression of Klotho can control the growth of T-cell lymphomas and decrease insulin-like growth factor-1 receptor (IGF-1R) signaling, which has anticancer properties." (PMID 39308872, 2024).
tongue cancer (4 papers, 2021 to 2025). A malignant neoplasm affecting the tongue. "The reliance of HNSCC on IGF1R coupled to Sdc1 was initially examined by screening the UM-SCC47 and SCC25 tongue carcinoma cell lines for their response to active or inactive mSSTNIGF1R peptides." (PMID 36968227, 2023).
Uterine leiomyoma (4 papers, 2010 to 2023). The presence of a leiomyoma of the uterus. "IGF1R was detected in the uterus and its expression levels were significantly higher in uterine fibroids." (PMID 30200635, 2018).
Allergy (3 papers, 2017 to 2022). An allergy is an immune response or reaction to substances that are usually not harmful. "Accordingly, IGF1R deficiency was reported to confer resistance to bleomicyn-mediated lung injury, house dust mite-induced allergy and lung tumor microenvironment pulmonary inflammatory response." (PMID 36353242, 2022). "In this regard, increased expression of p-ERK1/2 after HDM-induced allergy was attenuated upon treatment with the IGF1R TKI inhibitor NVP." (PMID 34440118, 2021). "Thus, IGF1R could have an important role in bone marrow mielopoiesis after HDM-induced allergy." (PMID 29272313, 2017).
amyotrophic lateral sclerosis (3 papers, 2020 to 2023). Amyotrophic lateral sclerosis (ALS) is a neurodegenerative disease characterized by progressive muscular paralysis reflecting degeneration of motor neurons in the primary motor cortex, corticospinal tracts, brainstem and spinal cord. "Insulin-like growth factor-1 receptor (IGF-1R) is a potential therapeutic target, because it is overexpressed in many cancers, AD, traumatic brain injury, amyotrophic lateral sclerosis (ALS), Friedreich ataxia and aging." (PMID 32283680, 2020). "Finally, we found that IGF1R inhibition can improve the deficits in signalling endosome transport observed in a mouse model of amyotrophic lateral sclerosis (ALS)." (PMID 32030864, 2020).
benign prostatic hyperplasia (3 papers, 2010 to 2015). A non-cancerous nodular enlargement of the prostate gland. "The aim of this study was to investigate the protective effect of metformin against experimentally-induced prostatic hyperplasia in rats with emphasis on its potential effects on certain key players of IGF-1/IGF-1R signaling pathway." (PMID 26492952, 2015). "Therefore, the aim of the current study was to investigate the protective effect of metformin against experimentally-induced prostatic hyperplasia in rats with emphasis on role of IGF-1/IGF-1R cascade." (PMID 26492952, 2015).
bone metastasis (3 papers, 2017 to 2025). Transfer of a neoplasm from its primary site to bones. "Further preclinical and clinical studies are needed to validate the safety and efficacy of targeting IGF-1R and other components of the signaling axis for the treatment of bone metastasis." (PMID 38342894, 2024). "A full understanding of the upstream mechanism of IGF-1R can better explain the occurrence of bone metastasis." (PMID 38342894, 2024). "In our study, elevated expression of IGF-1R was highly correlated with the development of bone metastasis in NPC patients and resulted in a worse survival prognosis." (PMID 38342894, 2024). "Future studies are warranted to evaluate IGF-1R blockade’s therapeutic potential and its effects on TAM plasticity in preclinical models of bone metastasis." (PMID 40394007, 2025).
bronchopulmonary dysplasia (3 papers, 2005 to 2021). Bronchopulmonary dysplasia is a chronic respiratory disease that results from complications related to lung injury during the treatment of infant acute respiratory distress syndrome in low-birth-weight premature infants or from abnormal lung development in older infants. "Increased expression of IGF-1 and IGF-1R from lung autopsy samples of babies who died from RDS and bronchopulmonary dysplasia suggests balanced IGF-1/IGF-1R being very important for lung development and maturation." (PMID 33917547, 2021).
Cerebral ischemia (3 papers, 2013 to 2016). Restriction of arterial blood supply to the brain associated with insufficient oxygenation to support the metabolic requirements of the tissue. "All modalities of neurological behavior measurement of ischemic rats receiving the specific IGF1R inhibitor (PPP) or CXCR4-Ab (mAb 173) injection in U-IGF1R+ hDSC-implanted group showed almost no recovery similar to that of the vehicle control after cerebral ischemia." (PMID 27586516, 2016).
Cirrhosis (3 papers, 2011 to 2025). A chronic disorder of the liver in which liver tissue becomes scarred and is partially replaced by regenerative nodules and fibrotic tissue resulting in loss of liver function. "Enterocytes: IPA analysis showed significant activation of inflammatory pathways (TNF, IFNG), PPARG/A with gut-liver signaling pathways (FGF21, IGF1R, CREBP) and fatty acid and lipid oxidation in compensated cirrhosis versus controls." (PMID 38369527, 2024).
desmoplastic small round cell tumor (3 papers, 2012 to 2020). Desmoplastic small round cell tumor (DSRCT) is an aggressive soft tissue cancer that typically arises in serous lined surfaces of the abdominal or pelvic peritoneum, and spreads to the omentum, lymph nodes and hematogenously disseminates especially to the liver. "In desmoplastic small round cell tumors (DSRCT) EWS-WT1 translocation induces a threefold over-expression of IGF-1R." (PMID 22415797, 2012).
diabetic encephalopathy (3 papers, 2014 to 2023). A brain disease that is characterized by functional impairment of cognition, cerebral signal conduction, neurotransmission and synaptic plasticity, and underlying structural pathology associated with diabetes. "It is concluded that insulin exerts direct anabolic actions in neuron-like cells by activation of its cognate receptor and proves that IGF-1R plays an important role of in the pathogenesis of diabetic encephalopathy." (PMID 26089889, 2015). "In summary, the low expression of IGF-1R could be help to inhibit diabetic encephalopathy to some extent." (PMID 26089889, 2015). "Based on these findings, we can speculate that, in diabetic encephalopathy, the effect of GIGYF2 on IGF1R signaling is not only mediated by cooperation with Grb10, but also by interaction with some other molecules." (PMID 25268761, 2014). "However, because insulin can cross-activate the insulin-like growth factor type 1 receptor (IGF-1R), which also functions in most of tissues, such as muscle and bone, it has been difficult to establish the direct (IGF-1-independent) actions of insulin in the pathogenesis of diabetic encephalopathy." (PMID 26089889, 2015).
diabetic neuropathy (3 papers, 2022 to 2025). A chronic, pathological complication associated with diabetes mellitus, where nerve damages are incurred due to diabetic microvascular injury involving small blood vessels that supply these nerves, resulting in peripheral and/or autonomic nerve dysfunction. "The expressions of IGF-1 and IGF-1R were dysregulated in diabetic patients and considered to be associated with the defects of peripheral nerve myelination in diabetic neuropathy." (PMID 40420926, 2025). "IGF-1R activation also activates mTOR signaling, which is necessary for the development of painful diabetic neuropathy." (PMID 37242543, 2023). "All these data indicated that spinal IGF-1/IGF1R signaling downregulated parallel to the development of painful diabetic neuropathy (PDN)." (PMID 35401920, 2022).
epilepsy (3 papers, 2019 to 2023). A brain disorder characterized by episodes of abnormally increased neuronal discharge resulting in transient episodes of sensory or motor neurological dysfunction, or psychic dysfunction. "Both loci include multiple potential candidate genes, including IGF1R, CNTNAP2, and DPP6, all are well‐studied genes that are strongly associated with developmental and speech delays, congenital heart disease, epilepsy, diaphragmatic hernia, renal anomalies, and ID." (PMID 31475484, 2019). "Furthermore, it can ameliorate the inflammation by inhibiting IGF1R, a tyrosine kinase receptor that activates PI3K and promotes Akt and mTOR pathways in pilocarpine-induced epilepsy in rats." (PMID 36672083, 2023).
esophageal adenocarcinoma (3 papers, 2015 to 2024). A malignant tumor with glandular differentiation arising predominantly from Barrett mucosa in the lower third of the esophagus. "Overexpression of IGF1R is prevalent in esophageal adenocarcinoma (EAC), as high as 75%, and has been associated with the progression of Barrett's to EAC." (PMID 26317790, 2015). "Function-altering polymorphisms in IGF1R as well as IGF1 microsatellite repeats and single strand nucleotide polymorphisms have been shown to affect risk for developing Barrett's esophagus and/or EAC." (PMID 26317790, 2015).
follicular adenomas (3 papers, 2019 to 2022). "Moreover, IGF‐1 and IGF‐1R protein and mRNA expression were significantly higher in follicular adenomas, nodular goiters, and PTC than those in the controls." (PMID 32851683, 2020).
growth disorders (3 papers, 2022 to 2024). "All these variants were identified in genes already associated with growth disorders: PROKR2 (N = 2), PTPN11 (N = 6), ANKRD11 (N = 1), NPR2 (N = 1), NF1 (N = 1), ACAN (N = 1), GH1 (N = 1), FBN1 (N = 1), COMP (N = 1), IGF1R (N = 1), ARID1A (N = 1), and CASR (N = 1)." (PMID 37605180, 2023).
Hepatitis C (3 papers, 2018 to 2025). "However, IGF1-R expression was detected in liver samples of patients with liver diseases including hepatitis C virus infection." (PMID 30206761, 2018).
hepatoblastoma (3 papers, 2013 to 2019). Hepatoblastoma (HB) is a malignant hepatic tumor and is the most common pediatric liver cancer. "The expression of IGF1R in all HGNET-BCOR tumors was stronger than in the hepatoblastoma sample." (PMID 31234291, 2019).
Huntington disease (3 papers, 2020 to 2023). Huntington disease (HD) is a rare neurodegenerative disorder of the central nervous system characterized by unwanted choreatic movements, behavioral and psychiatric disturbances and dementia. "The inhibitor-induced a reduction of p-IGF-1R and degradation of the IR substrates 1 and 2 (IRS1/2) leading to the enhanced stress resistance and protection against Aβ and polyQ40 proteotoxicity, AD and Huntington’s disease-associated proteins, respectively." (PMID 32719587, 2020).
influenza infection (3 papers, 2019 to 2025). "Phosphorylation of IGF1R exacerbates inflammation, and its overexpression increases cytokine levels during influenza infection." (PMID 35692833, 2022). "Thus, inhibiting IGF1 or IGF1R expression to block downstream signaling may be a novel treatment strategy for influenza infection." (PMID 31849847, 2019). "Overexpression of IGF1 aggravated cytokine expression during infection by influenza, while blocking of IGF1 production in mice treated with IGF1R inhibitor, decreased immunopathology." (PMID 31849847, 2019).
Intellectual disability (3 papers, 2016 to 2024). "The common signaling cascade reactions of IR/IGF1R include PI3K/AKT/mTOR and RAS/ERK, and the activation of these pathways plays a role in neurodevelopmental disorders such as intellectual disability (ID) and ASD." (PMID 39027477, 2024).
laryngeal carcinoma (3 papers, 2013 to 2021). Carcinoma that arises from the laryngeal epithelium. "In our cohort, consisted exclusively of patients with laryngeal cancer, the incorporation of IGFBP3 IHC expression did not improve the prognostic capacity of IGF1R alone." (PMID 23365645, 2013).
leiomyosarcoma (3 papers, 2012 to 2025). An uncommon, aggressive malignant smooth muscle neoplasm, usually occurring in post-menopausal women. "We sought to investigate the potential of miR-221, miR-320a, miR-133a, and miR-133b, along with their target mRNAs CDKN1B, TGFBR1, and IGF1R, as candidate biomarkers of leiomyosarcoma." (PMID 40630212, 2025). "The expression levels of miR-221, miR-320a, miR-133a, and miR-133b as well as their target mRNAs CDKN1B, TGFBR1, and IGF1R were assessed by quantitative real-time reverse transcription polymerase chain reaction (qRT-PCR) in tissue samples from 33 patients with leiomyosarcoma." (PMID 40630212, 2025). "The specificity of the IGF-1R/H3 association was further supported by a negative outcome of co-IP in the IGF-1R deficient leiomyosarcoma cell line SKUT-1." (PMID 27275536, 2016). "The target mRNAs CDKN1B, TGFBR1, and IGF1R in 25 leiomyosarcoma tumor tissues were not significantly deregulated." (PMID 40630212, 2025).
liver disease (3 papers, 2014 to 2025). "Understanding the interplay between PTEN, IR, and IGF1R is crucial for elucidating hepatic disease mechanisms." (PMID 40115165, 2025).
mantle cell lymphoma (3 papers, 2014 to 2017). Mantle cell lymphoma is a rare form of malignant non-Hodgkin lymphoma affecting B lymphocytes in the lymph nodes in a region called the ``mantle zone''. "In hematopoietic malignancies, a critical role was shown of the IGF-1/IGF-1R signaling pathway for proliferation and survival in multiple myeloma (MM) and mantle cell lymphoma (MCL)." (PMID 24489919, 2014).
metastatic prostate carcinoma (3 papers, 2014 to 2019). A carcinoma that arises from the prostate gland and has spread to other anatomic sites. "Several studies have reported that IGF1R expression is elevated in metastatic prostate cancer and hormone resistance progression." (PMID 24855559, 2014).
myeloproliferative neoplasm (3 papers, 2016 to 2023). A clonal hematopoietic stem cell disorder, characterized by proliferation in the bone marrow of one or more of the myeloid (i.e., granulocytic, erythroid, megakaryocytic, and mast cell) lineages. "Recent data indicate that IGF1R/IRS signaling is a potential therapeutic target in BCR-ABL1-negative myeloproliferative neoplasms (MPN); in this pathway, IRS2 is involved in the malignant transformation induced by JAK2V617F, and upregulation of IGF1R signaling induces the MPN phenotype." (PMID 32296029, 2020).
proliferative diabetic retinopathy (3 papers, 2013 to 2021). Advanced retinopathy due to diabetes mellitus characterized by the formation of new vessels in the retina. "Therefore, the present study focused on the assessment of mRNA levels of IGF1, IGF1R, and IGFBP3 both in ERMs and PBMCs from patients with proliferative diabetic retinopathy." (PMID 24379526, 2013).
schizophrenia (3 papers, 2021 to 2025). A major psychotic disorder characterized by abnormalities in the perception or expression of reality. "Among the FG loci with sex-homogeneous effects, variants at the MANBA/UBE2D3, NFATC3, and IGF1R provided insights into pathways involved in glucose homeostasis and relationships with other complex phenotypes, including neurodegeneration, schizophrenia, and cancer." (PMID 33402679, 2021). "IGF1R circRNAs were also found to be reduced in the peripheral blood of schizophrenia patients, suggesting its potential as blood-based marker with similar expression profile in brain tissue." (PMID 39966624, 2025). "IGF1R mRNA was found to be reduced in brain tissue from subventricular zone of schizophrenia patients potentially impairing the ability of neural stem and neuronal progenitor cells to respond to IGF1 during neurogenesis." (PMID 39966624, 2025).
serous ovarian carcinoma (3 papers, 2014 to 2024). "In two independent cohorts of serous ovarian carcinomas and oropharyngeal squamous cell carcinomas, stronger IGF1R/PCNA colocalization was significantly associated with a higher overall survival." (PMID 32701997, 2020). "The effects of BRCA1 on IGF1R were assessed in 121 serous ovarian cancer patients (BRCA1 mutation, n=30; non-BRCA1 mutation, n=32; hypermethylated BRCA1 promoter, n=28; and non-methylation, n=31)." (PMID 24765210, 2014). "IGF-1 and its receptor insulin-like growth factor 1 receptor (IGF-1R) are overexpressed in serous ovarian carcinoma; the activation of this signaling pathway enhances the proliferation and tumorigenicity in OC cell lines and is shown to be associated with chemoresistance." (PMID 39596005, 2024).
steatosis (3 papers, 2017 to 2025). Increased lipid within the cytoplasm of cells. "IR and IGF1R signaling contribute to steatosis induced by Pten ablation through distinct mechanisms." (PMID 40115165, 2025).
Thrombocytopenia (3 papers, 2011 to 2018). A reduction in the number of circulating thrombocytes. "Other grade 1 or 2 toxicities such as lymphopenia and thrombocytopenia are also commonly observed when anti-IGF1R antibodies are used and are increased when anti-IGF1R antibodies are used in combination with mTOR inhibitors." (PMID 21052545, 2011).
urothelial carcinoma (3 papers, 2020 to 2023). A malignant neoplasm derived from the transitional epithelium of the urinary tract (urinary bladder, ureter, urethra, or renal pelvis). "Additionally, one neoadjuvantly treated urothelial carcinoma was completely negative (as compared to two untreated cases with moderate IGF1R/PCNA signals)." (PMID 32701997, 2020).
adenoid cystic carcinoma (2 papers, 2019 to 2020). A malignant tumor arising from the epithelial cells. "Several chromosomal fusions, such as the MYB-NFIB fusion in adenoid cystic carcinoma, show dependence on IGF1R signaling, and IGF1R shows promise as a clinical target." (PMID 31980503, 2020).